CD7 (CD7 molecule)
Diseases named in the same sentence as CD7 in open-access papers (continued):
Sharing a sentence is not in itself a finding about the gene and the disease.
diffuse large B-cell lymphoma (4 papers, 2016 to 2025). "Follow-up immunohistochemistry also showed CD7 expression but this coexpression was confined to the large cells (specifically the areas involved by the diffuse large B-cell lymphoma)." (PMID 27774324, 2016). "This case is extremely rare and highlights the abnormal expression of the T-cell marker, CD7, in a diffuse large B-cell lymphoma arising in in a background of CD7 negative follicular lymphoma." (PMID 27774324, 2016). "The histologic and immunophenotypic findings are consistent with a CD7 positive diffuse large B-cell lymphoma arising in a background of a CD7 negative follicular lymphoma grade 3B." (PMID 27774324, 2016). "Only very rare cases of diffuse large B-cell lymphoma with aberrant expression of non-CD5 T-cell markers such as CD2 and CD7 have been reported, none of which to our knowledge have CD7 expression while arising in a background of a CD7 negative follicular lymphoma." (PMID 27774324, 2016).
graft versus host disease (4 papers, 2022 to 2025). An immune system disorder that occurs after allogeneic hematopoietic stem cell transplant and is a reaction of donor immune cells against host tissues. "Multiplexed knockouts prevented expression of αβ T-cell receptor (TCRαβ) to avoid graft-versus-host disease (GvHD), disrupted CD7 to evade self-targeting through the anti-CD7 CAR, and removed CD52 to confer resistance to the lymphodepleting antibody Alemtuzumab." (PMID 41034424, 2025).
Obesity (4 papers, 2019 to 2025). Accumulation of substantial excess body fat. "Since hematopoietic differentiation is influenced by epigenetic modulation of transcription factors, it suggests that epigenetic changes in the bone marrow induced by obesity and weight loss contribute to the generation of the active CD7+ monocytes." (PMID 40163180, 2025). "Compared to men with normal weight or with obesity, men with at least 10% weight loss have a significantly higher CD7-gene expression in immune cells of the bone marrow, and they have also a significantly higher number of peripheral CD7+ monocytes." (PMID 40163180, 2025). "It has been reported that persons with obesity have a significantly higher percentage of peripheral CD7+ monocytes than lean individuals." (PMID 40163180, 2025). "Thus, our nanoString screen suggests that in renal tumors from subjects with obesity, increases in CD36 and IDO1, with concomitant decreases in T cell-related CD7 and CCL21, are consistent with a host environment that favors tumor progression." (PMID 32469992, 2020). "Of those changes identified in the tumor microenvironments of ccRCC subjects with obesity versus non-obese counterparts, those with the largest fold changes were CD36 (+2.514, P = 0.045), IDO1 (+2.46, P = 0.012), CFB (+2.0, P = 0.041), CD7 (-4.66, P = 0.046), and CCL21 (-5.28, P = 0.0097)." (PMID 32469992, 2020).
Opportunistic infection (4 papers, 2016 to 2025). An infection that is caused by a pathogen that would generally not be able to cause an infection in a host with a normal immune system. "Still, CD7 targeting leads to the depletion of the majority of T cells, which brings considerable risk for potentially life-threatening opportunistic infections and would need to be managed according to established HSCT protocols." (PMID 36430170, 2022). "However, CD7-targeted T cell depletion renders the patient immune-deficient and therefore is associated with great risks for opportunistic infections during treatment." (PMID 36430170, 2022). "Early anti-CD7 CAR-T data showed expansion of naturally occurring CD7-negative T cells, but overall T cell numbers remained low with opportunistic infections and viral reactivation described, as well as deaths due to monocytopenia." (PMID 40238916, 2025). "Some studies believe that these CD7-loss T cells still perform a certain anti-infection function, but others believe that the cells are functionally deficient, which may cause viral reactivation (such as EBV and cytomegalovirus (CMV)) or other opportunistic infections after CAR-T cell treatment." (PMID 39609714, 2024). "CD7 is an ideal therapeutic target for two reasons: 1) there is a subset of CD7-negative peripheral normal T cells existed, which may maintain immune functions required for the prevention of opportunistic infections after the generated immunotoxin eliminates all CD7-positive cells." (PMID 27083001, 2016). "In the future, it will be necessary to explore whether CD7-loss T cells, especially newly emerging CD7-negative T cells after CD7 CAR-T cell treatment, remain resistant to opportunistic infections or how to improve the function of such T cells to improve patients' survival rates." (PMID 39609714, 2024). "However, double CAR-T cell infusions may increase the risk of viral and bacterial opportunistic infections in the long term, perhaps because of CD5 and CD7 double-negative T cells." (PMID 39609714, 2024).
Sézary syndrome (4 papers, 2005 to 2025). "Similarly, galectin expression along with its apoptosis-inducing counterreceptor CD7 explains the clonal selection toward CD4+CD7- T leukemic cells during progression of the Sézary syndrome." (PMID 24443956, 2014).
angioimmunoblastic T-cell lymphoma (3 papers, 2022 to 2023). A mature T-cell non-Hodgkin lymphoma, characterized by systemic disease and a polymorphous infiltrate involving lymph nodes and extranodal sites. "In a recently published experience, ten patients with R/R T-cell malignancies, including one patient with angioimmunoblastic T-cell lymphoma (AITL) and one with mycosis fungoides, were treated with anti-CD7 autologous and allogeneic CAR-T cells." (PMID 38201473, 2023).
autoimmune disease (3 papers, 2011 to 2025). A disorder resulting from loss of function or tissue destruction of an organ or multiple organs, arising from humoral or cellular immune responses of the individual to their own tissue constituents. "Applying this anti-CD5 and anti-CD7 CAR T cell treatment to autoimmune diseases with a strong T cell component could be a valuable treatment option." (PMID 39445021, 2024). "CD7- T-cells may also play a role in autoimmune disease evidenced by the increased CD4+CD7- cell expansion and accumulation reported in rheumatoid arthritis and psoriasis." (PMID 22126605, 2011). "It is likely that FDA approval will come first for the use of anti-CD5 and anti-CD7 CAR T cell therapies for T cell leukemias and lymphomas; however, this could help pave the way for its future use in treating patients with severe T cell-mediated autoimmune diseases." (PMID 39445021, 2024).
EATL type I (3 papers, 2012 to 2025). "An inflammatory background is absent, and necrosis is usually less evident than in classical EATL type I. Immunohistochemically, the tumor cells are CD3+, CD4-, CD5-, CD7+, CD8−/+, CD103+, TCRβ+/−, and contain cytotoxic granule associated proteins." (PMID 23217032, 2012).
melanoma (3 papers, 2017 to 2023). A malignant, usually aggressive tumor composed of atypical, neoplastic melanocytes. "In melanoma, SECTM1 is produced by tumor cells and attracts human monocytes via CD7-mediated activation of the PI3K pathway, leading to cancer progression by attracting monocytes or macrophages." (PMID 36818292, 2023). "Further, studies have shown that a ligand for CD7, SECTM1 (secreted and transmembrane protein 1), is highly expressed in many tumors, including melanoma cells." (PMID 29112124, 2017).
Pleural effusion (3 papers, 2013 to 2022). The presence of an excessive amount of fluid in the pleural cavity. "The ultrasound and chest x‐ray revealed a large right‐sided pleural effusion with monoblastic cells, aberrant expression of CD7 and in part CD56." (PMID 34382369, 2021). "The absence of CD3 and CD7 was more often seen in patients with ascites and pleural effusion involvement." (PMID 36160159, 2022).
T-lymphoblastic lymphoma (3 papers, 2021 to 2024). The most frequent type of lymphoblastic lymphoma. "We described successful treatment with preventive donor-derived anti-CD7 CAR-T therapy in a case of refractory T lymphoblastic lymphoma following allo-HSCT, who could not receive autologous anti-CD7 CAR-T products due to the low-quality of T lymphocytes." (PMID 38745670, 2024).
viral infection (3 papers, 2013 to 2024). "Various conditions such as viral infections, inflammatory disorders or other reactive conditions can result in downregulation of the pan T-cell marker CD7 and thereby mimic T-cell neoplasms." (PMID 32272749, 2020). "CCL14 and CD7 were among some of the most decreased proteins in viral infection." (PMID 37831367, 2024). "We describe a small aberrant CD8-weak/positive, CD7-negative/weak T-cell population that is associated with viral infections or with vaccination." (PMID 32272749, 2020).
breast carcinoma (2 papers, 2016 to 2018). "In our case, we confirmed the presence of a bladder metastasis from a primary breast carcinoma by confirming the presence of CD7 positivity, CD20 negativity, ER positivity, GCDFP-15 positivity, and HER2 positivity, in addition to the result of a pathological examination." (PMID 29987656, 2018). "The immunostaining results revealed CD7 positivity, CD20 negativity, ER positivity, and HER2 positivity, confirming a diagnosis of bladder metastasis from breast cancer." (PMID 29987656, 2018).
Burkitt lymphoma (2 papers, 2024). A rare form of malignant mature B-cell non-Hodgkin lymphoma. "Flow cytometric analysis with a PE anti-human CD7 antibody (BioLegend) showed that CD7 was highly expressed on the cell surface of T-ALL cell lines CCRF-CEM and Jurkat but not on the Burkitt lymphoma cell line Raji." (PMID 38254706, 2024).
chronic myelogenous leukemia (2 papers, 2010 to 2025). "Expression levels of the cell surface glycoprotein, CD7, and the serine protease, elastase 2 (ELA2), in the leukemic cells of patients with chronic myeloid leukemia (CML) have been associated with clinical outcome." (PMID 20175919, 2010).
COVID-19 (2 papers, 2021 to 2022). A disease caused by infection with severe acute respiratory syndrome coronavirus 2. "A significant decrease of total innate CD7+ lymphocytes characterized only the adult COVID-19 patients with a general impact on all CD56pos cells and on the frequency of the main NK cell subsets CD56high and CD56lowCD16high." (PMID 36466890, 2022). "Differently, elderly individuals with COVID-19 showed only little changes in the total count and frequency of innate CD7+ lymphocytes or NK cells." (PMID 36466890, 2022).
enteropathy (2 papers, 2011 to 2013). "We report a patient with an enteropathy associated with an aberrant CD8+CD7- T-cell IEL." (PMID 22126605, 2011). "In severe enteropathy, total number of CD7+ cells was significantly increased compared to samples from healthy controls, and a twofold increment in the number of MICA/B+lamina propria lymphocytes in untreated CD patients compared to healthy controls was found." (PMID 24058482, 2013). "The highest percentage (15.6%) of MICA+CD7+ cells per unit of m.m. was observed in biopsies from patients with mild enteropathy and the total number of MICA+CD7+ cells was 2.3 times higher than in control samples." (PMID 24058482, 2013). "Although there were not statistical differences between control and pathological samples, the mean percentage of MICA/B+CD7+ was higher in mild enteropathy samples." (PMID 24058482, 2013). "Surprisingly, in biopsies from patients with severe enteropathy we found the lowest percentages of CD7+MICA/B+ (2%)." (PMID 24058482, 2013). "We found coarse MICA/B aggregates in the cytoplasma of CD7+ cells; which were more frequently observed in mild enteropathy samples." (PMID 24058482, 2013). "Particularly, these CD7+MICA/B+ IELs were abundant in biopsies from patients with mild enteropathy." (PMID 24058482, 2013). "In addition, the total number of MICA/B+CD7+ cells in mild enteropathy was 4.2 times higher than in severe enteropathy, and among IELs, the number of CD7+ cells was twice higher in atrophy than that observed in mild enteropathy or control samples." (PMID 24058482, 2013). "Among CD7+lamina propria cells, MICA/B+ cells represented the 2.6% in controls, the 1.9% in severe enteropathy and the 7.6% in mild enteropathy." (PMID 24058482, 2013).
follicular lymphoma (2 papers, 2016 to 2017). Follicular lymphoma is a form of non-Hodgkin lymphoma characterized by a proliferation of B cells whose nodular structure of follicular architecture is preserved. "An association was described between hypomethylation of CD7 promoter region and its increased expression The orphan receptor tyrosine kinase ROR1 was shown to be expressed in follicular lymphoma." (PMID 28637510, 2017). "Here, we describe the first reported case of a DLBCL with abnormal expression CD7 arising in a background of follicular lymphoma in an 81-year-old male who presented with a nontender left axillary mass." (PMID 27774324, 2016). "Notably the areas involved by the follicular lymphoma were negative for CD7." (PMID 27774324, 2016).
HIV-1 infection (2 papers, 2013 to 2019). The type species of lentivirus and the etiologic agent of acquired immunodeficiency syndrome (AIDS). "The CD34+CD7+ progenitors were further analyzed to better understand their association with HIV-1 infection." (PMID 30761146, 2019). "By comparison, approximately 70% of CD7+CD56brightCD16neg immature NK cells express CXCR3, and HIV-1 infection is associated with a significantly lower frequency of CXCR3+ CD7+CD56brightCD16neg immature NK cells compared to healthy controls." (PMID 24351015, 2013). "HIV-1 infection was associated with a significant decrease in the frequency of CXCR3+CD7+CD56+CD16+ NK cells." (PMID 24351015, 2013). "On the other hand, the present study utilizing coculture of HIV-infected CD34+ cells and OP9-DL1 showed that CXCR4-tropic HIV-1 infection may also cause rapid depletion of CD34+CD7+CXCR4+ cells." (PMID 30761146, 2019). "During early HIV-1 infection, there is a significant expansion in the frequency of CD7+CD56negCD16+ NK cells that appears to persist into chronic HIV-1 infection; however, CD56negCD16+ cells remain a mixed myeloid and NK cell population." (PMID 24351015, 2013). "Our study has provided a more detailed understanding of the phenotype, function, and possible origin during chronic HIV-1 infection, of CD7+CD56negCD16+ NK cells in healthy and HIV-1-infected subjects." (PMID 24351015, 2013). "Further studies may be designed to test shorter coculture periods than 1 week and/or investigate the association of HIV-1 infection with factors that regulate the expression of CD3, CD4, CD7, and CD34." (PMID 30761146, 2019). "Interestingly, HIV-1 infection also resulted in a higher frequency of IFNγ secretion and degranulation by CD7+CD56negCD16+ NK cells in unstimulated conditions." (PMID 24351015, 2013). "One possible explanation for the expansion of this CD7+CD56neg NK cell subset is that during HIV-1 infection, the already rapid turnover of NK cells is further accelerated, preventing this subset of NK cells from terminally differentiating and gaining CD57 expression." (PMID 24351015, 2013). "CD7+CD56negCD16+ NK cells are significantly expanded in HIV-1 infection." (PMID 24351015, 2013). "However, HIV-1 infection resulted in a significant defect in IFNγ secretion in both NK cell subsets and in degranulation in CD7+CD56negCD16+ NK cells compared to CD7+CD56+CD16+ NK cells." (PMID 24351015, 2013). "An alternative hypothesis is that the expanded population of CD7+CD56negCD16+ NK cells during HIV-1 infection represents mature NK cells that arise at least in part when CD7+CD56+CD16+ NK cells engage target cells." (PMID 24351015, 2013). "During HIV-1 infection, CD7+CD56neg NK cells appeared to be mature; however, there were fewer CD57+ terminally differentiated CD7+CD56neg compared to CD7+CD56+ NK cells." (PMID 24351015, 2013). "KIR expression was not significantly altered on either CD7+CD56+ or CD7+CD56neg NK cells during HIV-1 infection compared to healthy donors." (PMID 24351015, 2013).
infectious mononucleosis (2 papers, 2015 to 2023). A condition characterized by an increase in mononuclear white blood cells and swollen lymph nodes, which is usually caused by infection with the Epstein-Barr virus. "Different from T cells in infectious mononucleosis, these T cells demonstrated more evident downregulation of CD5 antigen in addition to loss of CD7 and bright HLA-DR expression by immunophenotyping." (PMID 26451265, 2015).
large granular lymphocytic leukemia (2 papers, 2017 to 2022). "Typical immunophenotype of large granular lymphocytic leukemia (LGLL) included positive expressions of CD2, surface CD3 and CD8 (occasionally CD4), heterogeneous CD7, and over-/under-expression of CD5 but negative for CD25, CD26, and TCRγδ." (PMID 35299754, 2022).
lymphadenopathies (2 papers, 2020 to 2024). "We describe a novel peripheral blood T-cell subpopulation with a low light scatter and CD8-low, CD7-negative/low and CD3-positive marker expression profile, which indicates reactive T-cell expansion in patients who present with peripheral lymphadenopathy and/or B symptoms." (PMID 32272749, 2020).
myeloid sarcoma (2 papers, 2020 to 2025). A tumor mass composed of myeloblasts or immature myeloid cells. "Histopathology showed blast cell infiltration with strong CD7, CD38, CD43, CD45, and BCL-2 positivity, consistent with myeloid sarcoma." (PMID 41234969, 2025). "Histopathological evaluation revealed diffuse infiltration of blast cells in the submucosa with strong positivity for CD7, CD38, CD43, CD45, and BCL-2, mild positivity for CD33, and partial positivity for CD79a, CD68, CD117, and PAX5, consistent with myeloid sarcoma." (PMID 41234969, 2025).
neutropenia (2 papers, 2022 to 2024). A decrease in the number of neutrophils found in the blood. "CD7 CAR led to temporary neutropenia with a median time from infusion to recovery of absolute neutrophil count of 1,000/μL of 60 days." (PMID 36172388, 2022). "CD7 is not expressed in normal myeloid cells, so CD7 CAR-T cells will not lead to severe neutropenia." (PMID 39845313, 2024).
pancreatic cancer (2 papers, 2010 to 2022). "Even though CK20 is found in less than 20% of pancreatic cancers, most studies report the CD7+/CK20+ as the most common and the CK7+/CK20- as the second most common staining patterns, although the reverse has also been reported." (PMID 20302679, 2010).
Splenomegaly (2 papers, 2012 to 2017). Abnormal increased size of the spleen. "Serial transplantation of 1 500 CD34+CD2+CD7+Lin− cells sorted from a NOTCH1Mutated T-ALL (Patient 05) sample resulted in marked thymic enlargement, splenomegaly and pale marrows indicative of robust leukemic engraftment." (PMID 22768113, 2012).
T cell neoplasms (2 papers, 2019 to 2025). "Coexpression of CD2, CD4, CD7, and CD30 by the mast cells particularly in skin lesions may provoke misinterpretation as a cutaneous T-cell neoplasm." (PMID 31772790, 2019).
T-cell prolymphocytic leukemia (2 papers, 2019 to 2022). A slow-growing type of leukemia (blood cancer) in which too many lymphocytes are found in the bone marrow and/or blood. "T-cell prolymphocytic leukemia (PLL) cells were characterized by homogenously moderate CD2, CD5, and CD7, variable loss of surface CD3, moderate-to-dim CD26, heterogeneous CD25, and moderate TCL1." (PMID 35299754, 2022). "Marrow flow cytometry confirmed T-prolymphocytic leukemia with lymphocytes expressing CD2, CD3, CD7, CD52, and TCL-1." (PMID 31327318, 2019).
acute graft versus host disease (1 paper, 2020). A syndrome of immunologically mediated tissue damage that may occur following an allogeneic transplant, usually affecting the skin, liver, and GI tract. "Anti-CD3 and anti-CD7 were conjugated separately to RTA and mixed to treat steroid-refractory acute graft-versus-host-disease." (PMID 32182799, 2020).